IL6 (interleukin 6)
Diseases named in the same sentence as IL6 in open-access papers (continued):
Sharing a sentence is not in itself a finding about the gene and the disease.
endometriosis (continued). "Some studies have revealed that IL-6 could be a good marker for diagnosing endometriosis." (PMID 35571503, 2021). "In our opinion, the proposed panel of parameters, particularly IL-6, PRL and CA 125, could be a useful clinical tool to identify women with a high risk of endometriosis development, due to the enhanced expression of inflammatory biomarkers when compared to the healthy population." (PMID 33669013, 2021). "The evolution of endometriosis has been linked to a range of M1 macrophage polarization markers, including tumor necrosis factor α (TNF-α)—a marker with a strong inflammatory, cytotoxic and angiogenic potential, and IL-1β, IL-12, IL-8, IL-10 and IL-6, which promote the growth of endometrial cells." (PMID 34449536, 2021). "Also, the severity of endometriosis is correlated with levels of IL-6 in peritoneal fluid." (PMID 33209739, 2020). "Furthermore, one study evaluated the role of haptoglobin in endometriosis and determined that haptoglobin and IL-6 secreted by endometriosis cells decreased the adherence of peritoneal macrophages to the endometrial lesions and contributed to the pathophysiology of endometriosis." (PMID 33302392, 2020). "Furthermore, the downregulation of NK cell cytotoxicity by peritoneal fluid from women with endometriosis was also found to be attributed to interleukin 6 (IL-6) which was responsible for the inhibition of NK cell cytotoxicity and the downregulation of granzyme B and perforin expression." (PMID 31540116, 2019). "ROC curve analysis revealed the plasma levels of miR-17 was useful biomarker for differentiating women with and without endometriosis, the combination of miR-17, IL-4, and IL-6 could improve the diagnostic power." (PMID 29901577, 2018). "This study also indicated that the effects of IL-6 on cumulus cells and the oocyte, may be detrimental if elevated within the follicle at inappropriate or for extended periods of time, such as during chronic infections, endometriosis and in obese patients." (PMID 22536401, 2012). "Compared with untreated endometriosis, terazosin significantly reduced SF-1, PGE2, IL-6, IL-8, TNF-α, VEGF and HIF-1α across compartments (all p < 0.001), comparable to leuprolide (p = 1.000)." (PMID 42123670, 2026). "Research has shown increased levels of IL-1β, IL-6, and TNF-α in tissues affected by endometriosis, which confirms the crucial role of these cytokines in the disease’s pathophysiology." (PMID 40725782, 2025). "CD14 helps LPS recognize and activate TLR4, triggering the MyD88/NF-κB pathway, which promotes the release of IL-1, IL-6, and TNF-α, thus initiating systemic inflammatory cascades that contribute to the occurrence and progression of endometriosis." (PMID 40692689, 2025). "The analysis of these parameters in the ascitic fluid demonstrated that, according to macrophage polarization, IL-6 levels were significantly higher in the ascites of patients with HGS-OC than in those with other OC histotypes and endometriosis." (PMID 40723209, 2025). "AZM, acting potentially as both a senolytic and senomorphic (suppressing IL-6 SASP factor), also showed beneficial effects in a mouse model of endometriosis." (PMID 41145947, 2025). "Cytokines like IL6 and CXCL8/IL8 are found at abnormal levels in endometriosis and affect neutrophil recruitment and alter the peritoneal cavity microenvironment." (PMID 41009445, 2025). "Several cytokines, including vascular endothelial growth factor (VEGF), interleukin 6 (IL-6), and tumor necrosis factor α (TNF-α), have been studied in the pathogenesis of endometriosis." (PMID 39859551, 2025). "In this model, levels of interleukin 6 (IL6) and prostaglandin E2 (PGE2) were elevated, while levels of the serine protease inhibitor SERPINA1 were reduced in endometriosis‐like lesions." (PMID 40802848, 2025). "Systemic inflammatory markers (IL-6, CRP, fibrinogen, hepcidin, ferritin, and ROS) were markedly lower in endometriosis, consistent with a localized inflammatory process." (PMID 40723209, 2025).
endometriosis (continued). "Elevated levels of IL-6 and TGF-β1 in the peritoneal fluid of endometriosis patients are responsible for the impaired cytotoxic activity of NK cells." (PMID 40508002, 2025). "We present the first data on disease severity-associated changes in the serum levels of the growth factor EGF, the inflammatory cytokines MIF and IL-6, and the inhibitory sensory neuropeptide SOM in patients with endometriosis." (PMID 40724945, 2025). "Monocytes in women with endometriosis tend to produce higher levels of pro-inflammatory cytokines such as TNF-α, IL-1β, and IL-6." (PMID 41377340, 2025). "This activation suppresses IL-6 and TNF-α, which are two pro-inflammatory cytokines prominently involved in endometriosis pathophysiology." (PMID 40430189, 2025). "In endometriosis (EMs), ectopic lesions exhibit SNCs that sustain chronic inflammation and angiogenesis through SASP components (e.g. IL-6, MMP-3)." (PMID 41281750, 2025). "In a study published in 2014 in a mouse xenograft model of human endometriosis, PAR-2 inhibitor ENMD-1068 dose-dependently inhibited endometriotic lesion development and IL-6 and NF-κβ expression." (PMID 39982662, 2025). "Some studies demonstrated that proinflammatory cytokines such as IL-6, IL-8, and TNF-α participate in the pathogenesis of endometriosis." (PMID 40507929, 2025). "For example, in endometriosis, an excess of pro-inflammatory cytokines such as TNF-α and IL-6 contributes to chronic inflammation and tissue damage, disrupting the normal function of the reproductive organs." (PMID 41377340, 2025). "In endometriosis, for example, an excess of pro-inflammatory cytokines like TNF-α, IL-1β, and IL-6 leads to chronic inflammation and the formation of lesions outside the uterus, this can impair fertility." (PMID 41377340, 2025). "Immunological Effects: Antibiotic therapy reduces pro-inflammatory cytokines, such as IL-6 and TNF-α, in CE and endometriosis, mitigating the chronic inflammatory environment that fosters lesion survival." (PMID 40725782, 2025). "The analysis of circulating inflammation parameters demonstrated significantly lower levels of IL-6, fibrinogen, and CRP in patients with endometriosis than in those with HGS-OC and other OC histotypes." (PMID 40723209, 2025). "Moreover, IL-1β and IL-6 could be used as predictors for endometriosis." (PMID 39859551, 2025). "A high consumption of trans fatty acids has been shown to increase proinflammatory markers such as Interleukin 6 (IL-6) and Tumor Necrosis Factor Alpha (TNF-α), involved in the pathogenesis of endometriosis." (PMID 39062050, 2024). "Recently, we indicated that ASX significantly decreased serum levels of IL‐1β, IL‐6, and TNF‐α in endometriosis patients." (PMID 39479675, 2024). "Higher levels of cytokines or chemokines have also been described in patients with endometriosis, including macrophage migration inhibitory factor, TNF-α, IL-1β, IL-6 and IL-8." (PMID 39595086, 2024). "Previous studies have demonstrated that elevated expression of IL-6, IL-15, and TGF-β1 in patients with endometriosis can reduce the activity of NK cells." (PMID 38395801, 2024). "The downregulation of miR-138 expression enhances inflammation in endometriosis by elevating levels of TNF-α, IL-1β, IL-6, and IL-18 through the activation of the NF-κB signaling pathway and VEGF." (PMID 39001478, 2024). "Animal studies have demonstrated that gut microbiome plays a crucial pro-inflammatory role in the progression of endometriosis and results in higher levels of IL-1β, TNF-α, IL-6, and TGF-β1 and an increase in macrophages at the lesion site." (PMID 38627726, 2024). "In endometriosis, macrophages and mast cells have been found to release chemokines such as TNF and IL-6." (PMID 39536051, 2024). "Some studies have evaluated the follicular fluids of patients with endometriosis undergoing IVF, assessing the levels of IL-5, IL-6, and IL-3." (PMID 38337827, 2024).
endometriosis (continued). "Some studies have shown that endometriosis is a manifestation of pelvic inflammatory disease, with abundant inflammatory factors in the pathologic examination of endometriosis, such as IL-6, macrophage migration inhibitory factor, TNF-α, IL-1b, IL-6, and IL-8." (PMID 39536051, 2024). "DII scores were assessed for the role of food on inflammatory biomarkers, such as IL-6, C-reactive protein, and TNF-a, all of which increased in endometriosis." (PMID 39683382, 2024). "Vaccines using Bacillus Calmette–Guérin (BCG) are among the most effective immunotherapeutic agents that stimulate NK cells and prevent the typical IL6, IL10, and IL4 responses observed in endometriosis." (PMID 38543097, 2024). "One study showed that IL-37, an anti-inflammatory factor primarily produced by T-helper cells, acts as a trigger for pro-inflammatory factors such as IL-6, IL-8, and VEGF, thereby participating in the pathogenesis of endometriosis and enhancing angiogenesis." (PMID 38337827, 2024). "They produce cytokines such as IL-6, IL-10, and RANTES, among others, that have an important role in the proinflammatory environment, especially in endometriosis." (PMID 38892003, 2024). "MiR-196a may contribute to progesterone resistance in endometriosis and miR-144-3p has been shown to correlate with cell survival status in human endometriotic lesions and is involved in the regulation of inflammatory mediators such as IL-6, IL-1β, TNFα, PTGS2 and COX2." (PMID 39457531, 2024). "Dysregulation of proinflammatory cytokines (TNF-alpha, IL6...) or IL24 has been demonstrated to play an important role in the pathophysiology of eutopic and ectopic endometriosis." (PMID 38396681, 2024). "Endometriosis and cancer share a common inflammatory pathogenesis involving TNF-α, IL-1, IL-6, IL-8, and PGE2." (PMID 39458478, 2024). "Yet treatment of these endometriosis representative cell lines with rhLIF yielded the production of immune recruiting and inflammatory cytokines MCP-1, MCP-3, and IL-6, as well as the angiogenic factor VEGF." (PMID 37033980, 2023). "After the analysis, it was detected that the levels of IL-6, IL-10, IL-13, and TNF-α were significantly higher in women with endometriosis and infertility (P < 0.05)." (PMID 38601772, 2023). "The expression of IL-6, TNFα, and IL-1β, as markers of inflammation, and TGFβ, as a marker of fibrosis, could be useful tools to predict the response of an individual’s immune system to the different progestins suitable for the treatment of menopausal inflammatory disorders, including endometriosis." (PMID 37298830, 2023). "In endometriosis lesions, macrophages and mast cells have been found to release chemokines (such as TNF, IL-6, and IL-1 β) that play a key role in the neutrophil recruitment process." (PMID 37138868, 2023). "In animal models, curcumin has been shown to affect endometriosis through the HIF signaling pathway, whose key targets are HIF-1α, IL-6, and VEGFA, resulting in improved local hypoxia and reduced inflammation." (PMID 37375677, 2023). "The elevated concentrations of crucial pro-inflammatory cytokines, namely IL-1β, IL-6 and TNF-α, have been demonstrated in patients with endometriosis." (PMID 37143676, 2023). "It has been shown that the presence of IL-6 and TGF-β in the peritoneal fluid of endometriosis-affected women decreases the cytolytic ability of NK cells." (PMID 37936116, 2023). "On the other hand, cytokines secreted by B cells (such as IL-6, IL-17, and IFN-γ) also participate in the pathogenesis of endometriosis." (PMID 36865552, 2023). "The levels of TNF-α, IL-1, IL-6, IL-1β, and transforming growth factor β (TGF-β) in the TLR cascade are known to be altered in endometriosis patients." (PMID 37033937, 2023). "The anti-endometrial antibodies and chemokines secreted by B cells, such as IL-6, IL-17, and IFN-γ, also participate in the pathogenesis of endometriosis." (PMID 36865552, 2023).
endometriosis (continued). "There are other components of innate immunity, including TNF-α, IL-1β, IL-6, IL-17A, ICAM-1/LFA-1, and HMGB-1, that participate in the pathogenesis of endometriosis." (PMID 36865552, 2023). "High intake of tFAs is associated with higher levels of several inflammatory markers, such as IL-6 and TNF- α, which are thought to be involved in the pathogenesis of endometriosis." (PMID 36983810, 2023). "The validation results showed increased levels of miR-106b-3p, miR-451a, miR-486-5p, IL-6, IL-8, urokinase plasminogen activator (uPA), and tissue inhibitor of metalloproteinases type 1 (TIMP-1) in the peritoneal fluid from patients with endometriosis." (PMID 37834449, 2023). "In patients with mild to moderate endometriosis who are experiencing infertility, LIF expression was reduced in endometrial samples obtained during the mid-secretory phase, combined with elevated IL-6 and IL-1α in the peritoneal fluid (PF)." (PMID 37033980, 2023). "Cytokine activity, such as proinflammatory cytokines (IL-1β, IL-6) and tumor growth factor-beta (TNF-β), plays an important role in evading immune surveillance and predicting the disease severity of endometriosis." (PMID 36660246, 2023). "In the immune-related signaling pathways, there were several pathways, including “EGFR signaling pathway”, “IL-6 signaling pathway”, “JAK/STAT signaling pathway”, “MAPK signaling pathway”, “PI3K signaling pathway”, enriched in endometriosis." (PMID 36532015, 2022). "In endometriosis, PEA technology identified seven proteins up-regulated (IL-6, IL-8, CCL 19, SCF, VEGF-D, IL-6RA, MIA9) and ten proteins down-regulated (ICOSLG, EGFR, SELE, ErbB2/HER2, IL-6RA, VEGFR-2, Flt3L, CXCL10, HE4, FR-alpha)." (PMID 36009404, 2022). "Consumption of TFA increases circulating levels of inflammatory markers such as IL-6 and TNF-α, which are involved in endometriosis pathogenesis." (PMID 36138433, 2022). "Further, increased levels of TNF-α, IL-1β, IL-6, and IFN-γ have been detected in the serum, peritoneal fluid, and endometrium of women with endometriosis." (PMID 35409294, 2022). "The levels of inflammatory factors (like CRP, IL-6, IL-8, and TNF-a) in the peripheral blood and peritoneal fluid of patients with endometriosis are increased." (PMID 35800055, 2022). "Both IL-6 and transforming growth factor (TGF-β) in the peritoneal fluid of women with endometriosis have been shown to reduce the cytolytic activity of NK cells." (PMID 35805112, 2022). "Overexpression of IL6 enhances the migration and invasion ability of endometrial stromal cells by promoting EMT, which leads to the progression of endometriosis." (PMID 35565252, 2022). "Inflammatory cytokines such as IL‐6, LPS, and prostaglandins known as HGF inducers stimulate HGF production in the pelvic cavity of patients with endometriosis." (PMID 36259314, 2022). "In this study, the administration of ASCs also reduced the expression of IL-6, MCP-1, Lif-1, and TGF-β1, accompanied by the attenuation of endometriosis-like lesions." (PMID 35577867, 2022). "It has been proven that the stromal cells of eutopic endometrium in women with endometriosis are also characterized by high levels of transcripts and protein products, among others, for aromatase, cyclooxygenase (COX) 2 and interleukin 6 (IL-6)." (PMID 35409163, 2022). "The transcriptional activity of a number of proinflammatory cytokines/chemokines, such as IL-1, IL-6, IL-8, TNF-α, RANTES, MIF and ICAM1, is activated by NFκB signaling, demonstrating the key role of NFκB in the inflammatory response in endometriosis." (PMID 36359004, 2022). "Recently, IL-1β has been implicated to induce the production of proinflammatory cytokines, including IL-6 and IL-8, by increasing TDO2 expression in endometriosis." (PMID 35733134, 2022). "This study showed that letrozole combined with dydrogesterone can significantly reduce the levels of VEGF, CA125, E2, P, IL-6, and TNF-a in patients with endometriosis compared with the control group." (PMID 34901283, 2021).
endometriosis (continued). "Therefore, in this study, we decided to examine whether selected parameters of inflammation (IL-1β, IL-6, hs-CRP, IgG, YKL 40 and PRL) could become a set of additional diagnostic markers (all of them or some of them) supporting the diagnosis of advanced endometriosis." (PMID 33669013, 2021). "As can be seen, the concentrations of IL-6, IL-10, and TGF-β1/2 were found to be significantly higher in the peritoneal fluid of endometriosis patients as compared to the control group." (PMID 34501240, 2021). "Moreover, IL-6 secreted by endometriotic cells, in connection with interferon-γ, may upregulate the production of sICAM-1 (the soluble form of intercellular adhesion molecule-1) by macrophages in patients with endometriosis." (PMID 33669013, 2021). "We also showed that aberrant secretion of inflammatory substances, such as prostaglandin, interleukin (IL)-1β, IL-6, IL-8, and monocyte chemoattractant protein (MCP)-1, play essential roles in the pathophysiology of endometriosis." (PMID 34829748, 2021). "Concentrations of IL-6, IL-10, CCL2, CXCL8 and CXCL9 were significantly upregulated in the PF from women with endometriosis when compared to control women, whereas concentrations of other cytokines and chemokines were unaffected." (PMID 34360900, 2021). "Elevated levels of IL-10, IL-6, IL-8, COX-2, VEGF, and TNF-α have been observed in the peritoneal fluid of endometriosis subjects." (PMID 34769130, 2021). "The levels of some investigated cytokines and chemokines, such as IL-6, IL-10, CCL2, CXCL8, and CXCL9, were significantly increased in PF from patients with endometriosis as compared to control." (PMID 34360900, 2021). "Proinflammatory cytokines such as IL-1, IL-6, and TNF-alpha stimulate the synthesis of CRP which are found to be overexpressed in women with endometriosis as compared to controls." (PMID 34754275, 2021). "Significant differences in concentrations of IL-6 (p = 0.040), hs-CRP (p = 0.007) and CA 125 (p < 0.001) were observed in stage III vs. stage IV of endometriosis." (PMID 33669013, 2021). "Treatment was also associated with a decline in mRNA expression of several pro‐inflammatory cytokines including IL‐6, TNF‐α, IL‐1β and TGF‐β, known to be highly expressed in endometriosis." (PMID 31904910, 2020). "Several studies have already demonstrated, for example, that the peritoneal fluid of women with endometriosis has high levels of pro-inflammatory cytokines and growth factors, such as TNF-α, IL-1 and IL-6." (PMID 32192080, 2020). "IL-6, IL-8, and MIF significantly increased in endometriosis cases as compared with the control (p<0.05)." (PMID 33209739, 2020). "They found that IL-6, IL-10, IL-13, and TNF-α are highly expressed in the peritoneal fluid of endometriosis patients." (PMID 33354460, 2020). "Further, the upregulation of inflammatory factors IL6, IL8, and MCP1 has been found in the peritoneal fluid of women with endometriosis." (PMID 33233463, 2020). "One, 12Z spheroids secreted increased inflammatory factors, including IL6, IL8, and MCP1, compared to monolayer, which recapitulates what is seen in women with endometriosis." (PMID 33233463, 2020). "Our previous research suggested that oestrogen that up‐regulated in endometriotic lesions enhanced the expression of IL‐6 and TNF‐α via p38 MAPK pathway resulting in inflammatory response to promote endometriosis." (PMID 32725958, 2020). "Out of these nine cytokines, three have already been shown to be increased in the FF (IL1 β, IL6, and IL8), two in the peritoneal fluid (MCP-1 and basic FGF (FGF2)), and one in the serum of women with endometriosis." (PMID 32370059, 2020). "The levels of inflammatory cytokines, such as interleukin-6 (IL-6), interleukin-1β (IL-1β) and tumor necrosis factor alpha (TNF-α), are increased in the follicular fluid of patients with endometriosis." (PMID 31066787, 2019).